RABGAP1 (RAB GTPase activating protein 1)
Description:
May act as a GTPase-activating protein of RAB6A. May play a role in microtubule nucleation by centrosome. May participate in a RAB6A-mediated pathway involved in the metaphase-anaphase transition.
Synonyms: GAPCenA; TBC1D11
Tractability: PROTAC: ubiquitination databases record sites on it; its protein half-life has been measured.
Gene: Protein-coding gene on chromosome 9 (122,940,833 to 123,104,869, forward strand). Ensembl gene ENSG00000011454.
Subcellular location: Cytoplasm, cytosol; Cytoplasm, cytoskeleton, microtubule organizing center, centrosome
Subcellular location (Human Protein Atlas): Cytosol
Pathways (Reactome):
Vesicle-mediated transport: TBC/RABGAPs
Gene Ontology:
Molecular function: GTPase activator activity; protein binding; small GTPase binding; tubulin binding
Biological process: regulation of cilium assembly; regulation of GTPase activity
Cellular component: cytosol; centrosome; microtubule associated complex; cytoplasm
Genetic constraint (gnomAD): Loss-of-function variants: 19 observed, 115.88 expected, observed/expected ratio (o/e) 0.16, 90% interval 0.11 to 0.24. The upper end of that interval is the gene's LOEUF score, 0.24, which puts it in group 1 of 6, group 1 being the genes least tolerant of losing a copy. Missense variants: 849 observed, 1,213.5 expected, observed/expected ratio (o/e) 0.7, 90% interval 0.66 to 0.74. Synonymous variants: 422 observed, 429.87 expected, observed/expected ratio (o/e) 0.98, 90% interval 0.91 to 1.06.
Homologues: Orthologues: macaque RABGAP1 (99% identical), chimpanzee RABGAP1 (99% identical), pig RABGAP1 (99% identical), mouse Rabgap1 (97% identical), guinea pig RABGAP1 (97% identical), rabbit RABGAP1 (97% identical), rat Rabgap1 (97% identical), dog RABGAP1 (95% identical), tropical clawed frog rabgap1 (88% identical), zebrafish rabgap1 (78% identical). Paralogues in human: RABGAP1L (64% identical), TBC1D1 (16% identical), TBC1D4 (16% identical), TBC1D8B (15% identical), TBC1D9B (14% identical), TBC1D8 (14% identical), TBC1D9 (13% identical), EVI5L (13% identical), EVI5 (13% identical), TBC1D2B (13% identical), TBC1D10B (13% identical), TBCK (12% identical), and 33 more.
Diseases named in the same sentence as RABGAP1 in open-access papers:
RABGAP1 is named in the same sentence as 9 diseases in open-access papers, as found by Europe PMC text mining. Sharing a sentence is not in itself a finding about the gene and the disease. The quoted sentences say what the papers report.
breast carcinoma (1 paper, 2023). "The authors further reported that increased Rabgap1 mRNA levels were associated with a poor prognosis in human breast cancer patients." (PMID 37160609, 2023).
colorectal cancer (1 paper, 2024). A primary or metastatic malignant neoplasm that affects the colon or rectum. "Few studies have been conducted to investigate the role of the six genes that comprise the 3-GPS (IKBKB-DT, OR7E14P, PLXNA4, LOC401052, RABGAP1, and CTSV) in the context of chemotherapy for colorectal cancer." (PMID 39684481, 2024).
intellectual disabilities (1 paper, 2025). "However, biallelic loss of RABGAP1 in both humans and mouse models causes severe neurodevelopmental defects, including intellectual disabilities, global developmental delays, delayed myelination and loss of white matter volume in the brain." (PMID 40859033, 2025).
lung adenocarcinoma (1 paper, 2018). A carcinoma that arises from the lung and is characterized by the presence of malignant glandular epithelial cells. "We showed here that depletion of TUFT1 or RABGAP1 alleviated the accumulation of transport vesicles and lysosomes, which led to mTORC1 inactivation and tumor regression in A549 lung adenocarcinoma cells." (PMID 29423269, 2018).
microcephaly (1 paper, 2025). A congenital or acquired developmental disorder in which the circumference of the head is smaller than normal for the person's age and sex. "Functional analysis of patient cells revealed downregulated mTOR signaling and abnormal localization of early endosomes and lysosomes, while Rabgap1 knockout mice replicated microcephaly and corpus callosum dysgenesis." (PMID 39420677, 2025). "Biallelic variants in RABGAP1, the GTPase‐activating protein of RAB6A for retrograde transport from Golgi to ER, were reported in patients with global developmental delay, microcephaly, bilateral sensorineural hearing loss, seizures, corpus callosum dysgenesis, and facial dysmorphism." (PMID 39420677, 2025).
vitamin D deficiency (1 paper, 2021). A nutritional condition produced by a deficiency of VITAMIN D in the diet, insufficient production of vitamin D in the skin, inadequate absorption of vitamin D from the diet, or abnormal conversion of vitamin D to its bioactive metabolites. "Further studies are needed to identify variant SNPs in genes such as RABGAP1 (rs10818769, rs9409266) that reflect vitamin D deficiency in East Asians or Africans and to assess their modifiable roles for evolutionary differences." (PMID 34680925, 2021). "The pigmentation-associated allele evolution has been shown to include SLC24A5 and RABGAP1 in a previous study, and RABGAP1 was the signature gene for vitamin D deficiency and skin pigmentation." (PMID 34680925, 2021).
cancer (3 papers, 2019 to 2023). A tumor composed of atypical neoplastic, often pleomorphic cells that invade other tissues. "The more novel findings in this study were in genes (ARID5B, BAZ2B, RABGAP1, SFRP2, and WBP1L) that are associated with cancer risk and cellular differentiation." (PMID 36685876, 2022). "The acidic protein tuftelin 1 (TUFT1) is involved in mTORC1 activation by interacting with the RAB GTPase activating protein 1 (RABGAP1) and therefore may constitute a biomarker or a candidate for targeted therapy in mTOR activated, progressive cancers." (PMID 31261735, 2019). "Five of these genes (ARID5B, BAZ2B, RABGAP1, SFRP2, WBP1L) are associated with cancer risk and cellular differentiation and have not been previously identified in MS studies." (PMID 36685876, 2022).
tumor (3 papers, 2018 to 2022). "ARID5B, BAZ2B, RABGAP1, SFRP2, and WBP1L have not been previously associated with MS risk, and all are associated with neoplastic diseases and cellular proliferation." (PMID 36685876, 2022).
RABGAP1 also shares sentences with these, for which no sentence is quoted: Alzheimer disease (1 paper).